VWF (von Willebrand factor)
Description:
Important in the maintenance of hemostasis, it promotes adhesion of platelets to the sites of vascular injury by forming a molecular bridge between sub-endothelial collagen matrix and platelet-surface receptor complex GPIb-IX-V. Also acts as a chaperone for coagulation factor VIII, delivering it to the site of injury, stabilizing its heterodimeric structure and protecting it from premature clearance from plasma.
Synonyms: F8VWF; VWD
Tractability: Small molecule: it has a binding pocket of medium quality. Antibody: an approved drug acts on it; UniProt places it where antibodies can reach, with high confidence; its Gene Ontology location is reachable by antibodies, with high confidence; UniProt predicts a signal peptide or a membrane-spanning region. PROTAC: ubiquitination databases record sites on it. Other modalities: an approved drug acts on it.
Target class: Adhesion
Gene: Protein-coding gene on chromosome 12 (5,948,877 to 6,124,770, reverse strand). Ensembl gene ENSG00000110799.
Subcellular location: Secreted; Secreted, extracellular space, extracellular matrix
Pathways (Reactome):
Disease: Defective F8 binding to von Willebrand factor; Defective F8 cleavage by thrombin; Defective VWF binding to collagen type I; Defective VWF cleavage by ADAMTS13 variant; Defective binding of VWF variant to GPIb:IX:V; Enhanced binding of GP1BA variant to VWF multimer:collagen; Enhanced cleavage of VWF variant by ADAMTS13; Paradoxical activation of RAF signaling by kinase inactive BRAF; Signaling by BRAF and RAF1 fusions; Signaling by RAF1 mutants; Signaling by high-kinase activity BRAF mutants; Signaling by moderate kinase activity BRAF mutants; Signaling downstream of RAS mutants
Hemostasis: Amplification and propagation of coagulation cascade; GP1b-IX-V activation signalling; Initiation of coagulation cascade; Platelet Adhesion to exposed collagen; Platelet Aggregation (Plug Formation); Platelet degranulation; Regulation of clotting cascade
Signal Transduction: GRB2:SOS provides linkage to MAPK signaling for Integrins; Integrin signaling; MAP2K and MAPK activation; p130Cas linkage to MAPK signaling for integrins
Extracellular matrix organization: Integrin cell surface interactions
Gene Ontology:
Molecular function: collagen binding; identical protein binding; immunoglobulin binding; integrin binding; protease binding; protein binding; protein-folding chaperone binding; extracellular matrix structural constituent
Biological process: blood coagulation; cell adhesion; cell-substrate adhesion; hemostasis; platelet activation; positive regulation of intracellular signal transduction; response to wounding
Cellular component: endoplasmic reticulum; extracellular exosome; extracellular matrix; extracellular region; Weibel-Palade body; platelet alpha granule; platelet alpha granule lumen
Genetic constraint (gnomAD): Loss-of-function variants: 175 observed, 310.37 expected, observed/expected ratio (o/e) 0.56, 90% interval 0.5 to 0.64. The upper end of that interval is the gene's LOEUF score, 0.64, which puts it in group 2 of 6, group 1 being the genes least tolerant of losing a copy. Missense variants: 3,099 observed, 3,685.3 expected, observed/expected ratio (o/e) 0.84, 90% interval 0.81 to 0.87. Synonymous variants: 1,366 observed, 1,453.8 expected, observed/expected ratio (o/e) 0.94, 90% interval 0.9 to 0.98.
Gene-disease validity (ClinGen):
ClinGen rates the evidence that VWF causes each of these diseases.
hereditary von Willebrand disease (autosomal dominant): Definitive. Hereditary von Willebrand disease (VWD) is a hereditary bleeding disorder caused by a genetic anomaly leading to quantitative, structural or functional abnormalities of the Willebrand factor (von Willebrand factor; VWF).
von Willebrand disease type 2B (autosomal dominant): Definitive. A subtype of type 2 VWD characterized by a bleeding disorder associated with an increase in the affinity of the Willebrand factor (von Willebrand factor; VWF) for platelets.
Homologues: Orthologues: chimpanzee VWF (99% identical), macaque VWF (94% identical), dog VWF (86% identical), pig VWF (84% identical), mouse Vwf (83% identical), guinea pig VWF (83% identical), rat Vwf (82% identical), rabbit VWF (82% identical), tropical clawed frog vwf (55% identical), zebrafish vwf (46% identical). Paralogues in human: OTOG (25% identical), MUC5AC (23% identical), MUC5B (23% identical), OTOGL (21% identical), FCGBP (16% identical), MUC19 (15% identical), MUC6 (15% identical), MUC2 (14% identical), ZAN (13% identical), TECTA (13% identical), KCP (11% identical), CRIM1 (8% identical), and 7 more.
Diseases named in the same sentence as VWF in open-access papers:
VWF is named in the same sentence as 623 diseases in open-access papers, as found by Europe PMC text mining. Sharing a sentence is not in itself a finding about the gene and the disease. The quoted sentences say what the papers report.
endothelial dysfunction (418 papers, 2007 to 2026). In vascular diseases, endothelial dysfunction is a systemic pathological state of the endothelium (the inner lining of blood vessels) and can be broadly defined as an imbalance between vasodilating and vasoconstricting substances produced by (or acting on) the endothelium. "The combined effect of excessive platelet-mediated consumption and accelerated degradation due to endothelial dysfunction and shear stress results in a qualitative and quantitative deficiency of vWF, particularly the loss of HMW multimers." (PMID 40926892, 2025). "Von Willebrand Factor (vWF) is involved in coagulation, and in SCD, vWF levels are reported to be elevated due to ongoing haemolysis and endothelial dysfunction; increased vWF levels have also recently been found associated with VOCs and acute chest syndrome." (PMID 39912492, 2025). "It is less effective in evaluating coagulopathy associated with endothelial dysfunction, platelet adhesion, and von Willebrand factor activity – important components of the immunothrombotic process." (PMID 40612950, 2025). "Our results support the view that circulating the vWF reflects underlying endothelial dysfunction, a critical process in atherosclerosis progression." (PMID 41007843, 2025). "From a clinical point of view, there is no doubt about the high thrombogenicity of SARS-CoV-2 due to endothelial dysfunction, causing elevated levels of prothrombotic substances such as D-dimer or VWF in critical COVID-19 patients." (PMID 41585277, 2025). "Endothelial injury is also common in these patients, and von Willebrand factor (vWF) serves as a recognized marker of endothelial dysfunction, contributing to thrombotic risk and microvascular impairment." (PMID 41049335, 2025). "Markers associated with endothelial dysfunction, such as von Willebrand factor antigen, soluble P-selectin, and thrombomodulin, hold promise as indicators of endothelial injury and coagulation abnormalities in COVID-19." (PMID 39359765, 2024). "Of note, our mediation analysis indicates that vWF, which is a marker of endothelial dysfunction, significantly contributes to the risk of mortality in the prediabetes high-risk cluster." (PMID 39175055, 2024). "Loss of endothelial integrity results in the release of VWF, a clear indicator of endothelial dysfunction." (PMID 38399555, 2024). "Activation of the integrin αvβ3-FAK/Src pathway likely underlies vWF-induced endothelial dysfunction in sepsis." (PMID 38921594, 2024). "After cardiac surgery, AF is linked to a higher risk of illness and death, and vWF is regarded as an indicator of endothelial dysfunction or damage." (PMID 38397876, 2024). "Further, in the landscape of biomarkers linked to endothelial dysfunction, the circulating inflammatory coagulation markers assume a pivotal role, notably the fibrin(ogen), D-dimer, P-selectin, and von Willebrand Factor (VWF)." (PMID 38077924, 2023). "This change increases O2– and a positive feedback process between the OS and the inflammatory process that, in turn, causes endothelial dysfunction, favoring the increase in von Willebrand factor and causing thrombosis." (PMID 37111348, 2023). "Studies have suggested that high expression of VWF is closely associated with the development and progression of ischemic cerebrovascular diseases through thrombus formation and endothelial dysfunction." (PMID 37415610, 2023). "In the intricate landscape of biomarkers linked to endothelial dysfunction, certain circulating inflammatory coagulation biomarkers assume a pivotal role, notably the fibrin(ogen), D-dimer, P-selectin, and von Willebrand Factor (VWF)." (PMID 38077924, 2023). "This study, to our knowledge, is the first to show elevated vWF associated with reduced FMD as a marker of endothelial dysfunction in youngsters with newly diagnosed GD." (PMID 37022495, 2023).
endothelial dysfunction (continued). "From a mechanistic point of view, hypercoagulability is associated with elevated vWF, endothelial dysfunction, elevated fibrinogen and factor VIII levels, and reduced thrombomodulin levels." (PMID 37507773, 2023). "So it is advised to measure the plasma levels of vWF in all children with overt hyperthyroidism in order to identify extent of endothelial dysfunction with early diagnosis and follow-up so as to reduce risk of cardiovascular and thromboembolic complications." (PMID 37022495, 2023). "vWF is abundantly expressed in cerebrovascular endothelium and associated with enhanced inflammatory activity, promoting endothelial dysfunction and cerebral amyloid angiopathy pathology." (PMID 36471423, 2022). "Plasma kynurenine levels were positively associated with thrombomodulin and von Willebrand factor (markers of endothelial dysfunction)." (PMID 35448889, 2022). "The vWF ADAMTS13 axis is likely impaired because of endothelial dysfunction caused by the SARS- CoV-2 -induced activation of endothelial cells, leading to a significantly higher and independent risk of preterm delivery in this setting." (PMID 35189860, 2022). "Vascular remodeling was potentially caused by endothelial dysfunction demonstrated by elevated von Willebrand factor (vWF) concentration in plasma and reduced vWF staining in lung tissue with platelet depletion." (PMID 36016884, 2022). "As a result, biomarkers of endothelial dysfunction such as plasma VWF are elevated and associated with the presence of these deranged metabolic profiles." (PMID 36613770, 2022). "In cirrhosis, VWF antigen has been established as a valuable parameter for risk stratification, indicating endothelial dysfunction and inflammation." (PMID 34945736, 2021). "Nonetheless, COVID-19 disease progression is consistent with endothelial dysfunction and increased plasma VWF levels and VWF:AG/ADAMTS13 activity ratios are associated with COVID-19 disease severity and reported to be a predictor of morbidity and mortality." (PMID 35087853, 2021). "It has been proposed that these complications are secondary to COVID-19-induced endothelial dysfunction that cause the imbalance between limited vWF-cleaving protease and elevated exocytosis of vWF from ECs." (PMID 34176095, 2021). "GH can cause an increase in the plasma level of von Willebrand factor, a marker of endothelial dysfunction." (PMID 35059575, 2021). "Further, MDD has an adverse effect on endothelial function; for example, circulating markers of endothelial dysfunction (e.g., soluble adhesion molecules, von Willebrand factor) have been linked with depression." (PMID 32230840, 2020). "Pathogenic mechanisms, including endothelial dysfunction with increased levels of von Willebrand factor, systemic inflammation with Toll-like receptor activation, and a procoagulatory state via tissue factor pathway activation, are involved." (PMID 33146040, 2020). "Several studies have reported that high plasma vWF levels are associated with endothelial dysfunction and inflammation, which contribute to the cardiovascular risks." (PMID 32039706, 2020). "Plasma von Willebrand factor (vWF; an endothelial activation marker) and endothelin-1 (ET-1; an endogenous vasoconstrictor strongly linked with endothelial dysfunction) were measured." (PMID 33080821, 2020). "Increased VWF protein expression has been reported in EC after gamma-radiation and is associated with endothelial dysfunction, and lung and heart pathophysiology." (PMID 30978983, 2019). "Our data on the association between BDNF and vWF support endothelial dysfunction as an important determinant of low BDNF levels in stable CAD patients." (PMID 29409455, 2018). "High level of vWF is partly due to endothelial dysfunction and atherosclerosis, and it is associated with an increased risk of coronary artery disease." (PMID 29915535, 2018).
endothelial dysfunction (continued). "Endothelial dysfunction and activation, vascular aging, and arterial stiffness are all associated with increased levels of VWF." (PMID 28634421, 2017). "A strong association was also seen between EDS and elevated vWF (marker of endothelial dysfunction) and low FEV1, markers associated with HF." (PMID 28674146, 2017). "VWF is a marker of endothelial dysfunction, which is thought to explain the association between VWF levels and diabetes." (PMID 27787621, 2017). "Data suggesting a significant component of endothelial dysfunction were reported by Okon and colleagues in 2004; vWF staining on distended veins remained intense, despite loss of endothelial-dependent relaxation." (PMID 27713879, 2016). "Increased levels of VWF, a biomarker of endothelial dysfunction, have been associated with renal disease in type 1 (DM1) and type 2 diabetes mellitus (DM2)." (PMID 26770985, 2016). "vWF is involved in platelet adhesion, coagulation factor VIII binding and transport, and formation and deposition of thrombus, and elevated vWF concentrations have been shown to be associated with endothelial dysfunction and/or injury." (PMID 26769594, 2016). "Insulin resistance is associated with systemic inflammation and markers of endothelial dysfunction, including tissue plasminogen antigen (tPA) and von Willebrand factor (vWF), which have been related to diabetes incidence." (PMID 26158609, 2015). "MAU is also associated with biochemical indices of endothelial dysfunction, such as an increased von-Willebrand-Factor (VWF) and increased platelet adhesiveness." (PMID 26362770, 2015). "Based on the evidence that these biomarkers are associated with endothelial dysfunction and hypercoagulability, this study aimed to investigate the relationship among VWF, ADAMTS13, and D-Dimer with different levels of renal dysfunction in DM1 patients." (PMID 26168189, 2015). "In contrast to previous study, vWF levels in our study reached their maximum after 24 h, and remained unchanged 48 h after procedure suggesting prolonged endothelial dysfunction and increased risk for early thromboembolic events within first 48 h." (PMID 25390649, 2014). "The presence of albuminuria was associated with biochemical indexes of endothelial dysfunction, such as increases in the serum levels of von Willebrand factor, endothelin, tissue plasminogen activator, and fibrinogen." (PMID 24788677, 2014). "We found a strong independent association between periatrial EAT and markers of endothelial dysfunction as measured by vWF and sICAM1." (PMID 24143210, 2013). "Periatrial epicardial fat showed a significant positive association with increased levels of sICAM-1 and vWF, which are biomarkers of endothelial dysfunction." (PMID 24143210, 2013). "Considering that endothelial dysfunction, as measured by vWF blood levels, is strongly associated with AF-related strokes, this result is clinically relevant." (PMID 24143210, 2013). "A broad array of disorders of brain vessels have been associated with endothelial dysfunction, which results in increases in vWF secretion." (PMID 24086636, 2013). "Endothelial dysfunction indicated by elevation of vWF, ICAM-1, or VCAM-1 was associated with significantly higher AF than in diabetic patients with normal levels of these parameters." (PMID 23671885, 2013). "We explored these polymorphisms in a case-control study and evaluated endothelial dysfunction by measuring several biomarkers including VWF, VCAM-1 and thrombomodulin, as well as the soluble form of CX3CL1." (PMID 19587779, 2009). "Obesity is associated with increased blood concentrations of endothelial dysfunction markers such as fibrinogen and Von Willebrand factor (vWF), associated with hypercoagulability." (PMID 17425777, 2007). "In one study, circulating t-PA antigen correlated strongly with circulating levels of von Willebrand factor (vWF), another endothelial release product, as well as with risk markers associated with endothelial dysfunction." (PMID 19690642, 2007).